NRAS (NRAS proto-oncogene, GTPase)
Diseases named in the same sentence as NRAS in open-access papers (continued):
Sharing a sentence is not in itself a finding about the gene and the disease.
melanoma (continued). "BRAF/NRAS wild-type and NF1 mutant melanomas are strongly associated with UV damage, as evidenced clinically by the higher degree of solar elastosis and, at a molecular level, by a high proportion of C > T transitions at pyrimidine dimers and more frequent tandem CC>TT transitions." (PMID 28637487, 2017). "Furthermore, on the basis of analyses of somatic co-mutation patterns in the TCGA data sets (cBio Portal for Cancer Genomics), 9.6% of melanomas with NF1 mutations also have mutations in BRAF, NRAS or RAF1." (PMID 28637487, 2017). "Here HGF rescued four of six NRAS mutant melanoma cell lines from MEK inhibition." (PMID 28147313, 2017). "As the studies of the major genomic aberrations in melanoma have been extensively reviewed elsewhere, this section will describe a number of the most common driver mutations seen in cutaneous melanoma [BRAF, NRAS, NF1, microphthalmia-associated transcription factor (MITF), and PTEN]." (PMID 29276510, 2017). "Combined kinase and DUB inhibition was effective in completely suppressing NRAS-mutant melanoma in vivo, suggesting combination therapy may prevent resistance mediated by Ets-1 induction." (PMID 28198367, 2017). "In addition, NRAS-mutant melanoma patients showed a higher frequency of nodal relapse (p = 0.013) and development of metastatic disease (p = 0.021)." (PMID 28797232, 2017). "Finally, other less frequently mutated melanoma genes (KRAS, HRAS, KIT, GNAQ, GNA11) were enriched in tumors wild‐type for BRAF, NRAS, and NF1." (PMID 28267273, 2017). "To investigate the molecular mechanisms underlying this differential requirement of RAF kinases at different stages of melanomagenesis, we used in situ proximity ligation assays (PLA) to look at the ability of endogenous BRAF and CRAF to interact with NRAS first in cells from full-blown melanoma." (PMID 28497782, 2017). "NRAS amplification was a rare alteration and observed in 6.7% of melanoma samples (7/101)." (PMID 28668077, 2017). "In melanoma, CRISPR screens have looked for genes whose loss confers resistance to the BRAF inhibitor vemurafenib, identifying targets such as NF1, whose loss results in activation of NRAS, a recognized vemurafenib resistance mechanism." (PMID 28097822, 2017). "Here, we applied single-cell RNA-seq to measure the transcriptomes of 307 single cells cultured from three biopsies of three different patients with a BRAF/NRAS wild type, BRAF mutant/NRAS wild type and BRAF wild type/NRAS mutant melanoma metastasis, respectively." (PMID 27903987, 2017). "Thus, in melanoma, one sample (6.2%) had an uncommon BRAF (c.1400C>T; p.Ser467Leu) mutation, one (6.2%) had an NRAS (c.385C>T; p.Gln129*) mutation, and rare EGFR, ERBB2, KRAS, and MET mutations were also exhibited in one sample (6.2%)." (PMID 28404952, 2017). "Also, a report on whole‐exome sequencing identified NF1 as the third most frequently mutated gene in melanoma after BRAF and NRAS, occasionally concurrently with other RASopathy gene mutations." (PMID 28267273, 2017). "In an attempt to search for new compounds that could partner with kinase inhibitors for inhibition of NRAS mutant melanoma, we combined α-Mangostin with a series of kinase inhibitors to treat the NRAS mutant melanoma cell line SK-MEL-2." (PMID 27152946, 2016). "Importantly, this finding suggests that MAP kinase pathway inhibition can – in principle –constitute a viable treatment option for a subset of BRAF/NRAS wild type melanomas." (PMID 27273450, 2016). "Based on these results, we asked if IFI6 is necessary for NRAS-mutant melanoma-driven tumor growth." (PMID 27608486, 2016). "Because we had observed that the MAPK pathway regulates IFI6, we tested whether pharmacological MEK inhibitors could be combined with DNA replication stress-inducing drugs to treat NRAS-mutant melanoma." (PMID 27608486, 2016). "Our studies have identified a novel and clinically significant feature of NRAS-mutant melanoma." (PMID 27608486, 2016).
melanoma (continued). "Actually NRAS and BRAF mutations are the most frequent oncogenic mutations found in melanoma." (PMID 27833586, 2016). "Thus, the ability of IFI6 to regulate DNA replication stress originates in its ability to repress E2F2 and its target genes specifically in the context of NRAS-mutant melanoma." (PMID 27608486, 2016). "Based on these results, we tested whether immortalized melanocytes expressing NRASQ61K behaved similarly to the NRAS-mutant melanoma cells and primary human melanocytes that show regulation of E2F2 and its target genes." (PMID 27608486, 2016). "Therefore, the DNA replication stress pathway represents a unique vulnerability of NRAS-mutant melanoma that can be pharmacologically inhibited to achieve tumor inhibition in cell culture and in vivo." (PMID 27608486, 2016). "Indeed, the depletion of MITF from MITF-expressing NRAS mutant melanoma cells significantly sensitized these cells to MEK inhibition." (PMID 26977879, 2016). "We observed the same results in two additional NRAS-mutant melanoma cell lines, M318 and SKMEL-103." (PMID 27608486, 2016). "However, NRAS-mutant melanoma currently lacks effective targeted therapies, and targeting the pro-survival pathways downstream of oncogenic NRAS (e.g., PI3K or MEK inhibitors) have not been successful." (PMID 27608486, 2016). "The mutational status for BRAF, NRAS and c-KIT was assessed in the melanoma samples." (PMID 26909610, 2016). "We treated NRAS-mutant (YUGASP, SKMEL-2, SKMEL-103, and M318), BRAF-mutant (SKMEL-28 and A375), NF1-mutant/null (MeWo and YUTOGS), and NRAS/BRAF/NF1 wild-type (YUVON) melanoma cells with three DNA replication stress-inducing agents: aphidicolin, camptothecin, and hydroxyurea." (PMID 27608486, 2016). "Several studies could show that mutant NRAS activates the PI3K/mechanistic target of rapamycin (mTOR)-signaling cascade in melanoma and lung cancer." (PMID 26821351, 2016). "The most frequent melanoma-associated genetic events in PI3K-AKT signaling pathway are inactivating mutations (often related only to exons 9 and 20 of PIK3CA) or PTEN loss of expression or mutations and activating NRAS mutations." (PMID 26863566, 2016). "Nelfinavir profoundly sensitizes BRAF and NRAS mutant melanoma cells to MAPK-pathway inhibitors." (PMID 26977879, 2016). "In addition, treatment with the MEK inhibitor trametinib, which reduces IFI6 expression, when combined with drugs that induce DNA replication stress, potently inhibited NRAS-mutant melanoma tumor growth in cell culture and in mice." (PMID 27608486, 2016). "NRAS mutations have previously been associated with UV-associated DNA damage, but are not frequently observed in melanomas containing high UV-induced mutation loads." (PMID 27191502, 2016). "Therefore, NRAS exon 2 and BRAF exon 15 variants represented the two most frequently mutated exons in NZ melanomas." (PMID 27191502, 2016). "In fact, NRAS mutations do not result in melanoma according to in vitro and in vivo preclinical models and to the evidence of mutated cells in CMN." (PMID 27439913, 2016). "Thus, a better understanding of NRAS-mutant melanoma is required for developing effective targeted therapies." (PMID 27608486, 2016). "The importance of ER homeostasis in melanoma is highlighted by the constitutive upregulation of certain ER-resident chaperones, such as GRP78, and their correlation with upstream, disease initiating, NRAS, or BRAF oncogenic mutations." (PMID 27896217, 2016). "The MAPK pathway is activated mainly through oncogenic mutations of BRAF or NRAS, which are early events in melanoma development and in absence of other alterations lead to oncogene induced senescence." (PMID 27449293, 2016). "This consequentially inhibits mutant NRAS-induced melanocyte transformation and melanoma growth." (PMID 27608486, 2016). "Thus, new therapeutic approaches for treating NRAS-mutant melanoma and other RAS-mutant cancers are needed." (PMID 27608486, 2016).
melanoma (continued). "Finally, we show that NRAS-mutant melanomas are significantly more resistant to cytotoxic agents that function by inducing DNA replication stress than wild-type NRAS melanoma cells." (PMID 27608486, 2016). "discover PAX3-mediated overexpression of MITF as a reversible resistance mechanism to MAPK-pathway inhibition in BRAF mutant melanomas and identify nelfinavir, which inhibits this mechanism and sensitizes not only BRAF mutant but also BRAF and NRAS mutant melanoma cells to MAPK-pathway inhibitors." (PMID 26977879, 2016). "This was again consistent for all the melanoma cell lines tested irrespective of the mutation status of BRAF or NRAS." (PMID 27829238, 2016). "Based on these findings, we hypothesized that the loss of IFI6 results in dysregulated DNA replication via E2F2 upregulation, which in turn blocks NRAS-mutant melanoma tumor growth and melanomagenesis." (PMID 27608486, 2016). "Melanomas arising in visceral organs are less likely to be BRAF or NRAS positive." (PMID 26169921, 2015). "Overall, MAPK and NRAS subtypes represent vast majority of melanoma cases." (PMID 26322273, 2015). "Reasonably a similar mechanism of resistance may exist in some of the NRAS mutant melanomas and therefore treating them with a combination of MEKi + PI3Ki may provide beneficiary effects." (PMID 25645078, 2015). "In the context of melanoma, somatic splice-site mutation of TMEM216 suggests potential tumor suppressor function and sets the RHOA/GNA12 pathway apart from the Gs-protein/MAPK pathway by mutual exclusivity of TMEM216 towards known oncogenes NRAS and RAC1." (PMID 25600636, 2015). "Moreover, it appears that ECAD is more abundant in the cytoplasm of NRAS-ΔPTEN melanoma cells than in NRAS cells, and less at the cell–cell contact." (PMID 26307673, 2015). "Melanomas are characterized by activating “driver” mutations in BRAF, NRAS, KIT, GNAQ, and GNA11." (PMID 26084293, 2015). "NRAS mutation is detected in around 20% of melanomas; however no effective direct inhibitor of mutated NRAS is clinically available." (PMID 25645078, 2015). "Altogether our data demonstrates that prenylation inhibition may be a novel therapeutic approach in NRAS mutant melanoma." (PMID 25646931, 2015). "We found that the RICTOR locus is frequently amplified and overexpressed in melanoma and that RICTOR over-expression in NRAS-transformed melanocytes stimulates their clonogenicity, demonstrating that RICTOR amplification can cooperate with NRAS mutation to stimulate melanoma proliferation." (PMID 26356562, 2015). "Furthermore, based on our preclinical findings, additional prenylation inhibitors need to be developed or investigated that have improved pharmacological properties in order to be effective against NRAS mutant malignant melanoma." (PMID 25646931, 2015). "However, Gab2 is co-expressed with NRAS in melanoma cell lines and tumor samples, and its expression correlates with metastatic potential." (PMID 26095858, 2015). "A differential effect of immune therapy by genotype has been observed clinically; retrospective studies suggest that NRAS-mutant melanomas may respond better to immune therapy compared to other genetic cohorts." (PMID 25537510, 2015). "The aim of this study was to investigate the prevalence and distribution of pathogenetic variants in BRAF, NRAS, and PIK3CA genes among 245 DNA samples from pigmented melanomas of cutaneous origin, defining the fraction of cases harboring coexistent PIK3CA and BRAF or NRAS mutations." (PMID 25627962, 2015). "However, the short duration of the response and progression free survival in these patients indicate that combination therapy strategies are needed to be designed for NRAS mutant melanomas." (PMID 25645078, 2015). "In BLM (NRAS-mutant) cells, activation of this receptor, by means of agonistic ligands, induces its translocation into the nucleus and initiation of transcriptional activity, thereby significantly and specifically decreasing melanoma cell proliferation." (PMID 26225426, 2015).
melanoma (continued). "Actually, NRAS and BRAF mutations are very frequently found in melanoma tumors; in particular, BLM cells are NRAS-mutant (a mutation present in about 30% of patients), while both A375 and WM1552 cells harbor the BRAF V600E mutation (the predominant BRAF mutation, occurring in about 50% of cases)." (PMID 26225426, 2015). "Multiple RAFi and MEKi (e.g., PD-0325901, Trametinib) resistance mechanisms, which may involve alterations in NRAS/ERK pathway (e.g., NRAS mutations, switching between RAF isoforms) or parallel pathways (e.g., PTEN loss), have been discovered in melanoma." (PMID 26284497, 2015). "Our findings imply that MEK inhibition might enhance vulnerability of NRAS mutant melanoma cells to DNA damage induced not only by radiation, but also by chemotherapy." (PMID 26136337, 2015). "Our analysis of the exome re-sequencing data from the same TCGA cohort did not identify specific enrichments for mutations in BRAF, NRAS or any of the other well-established melanoma driver genes (n=116) in either of the clusters." (PMID 25865119, 2015). "However, in the case of NRAS mutant melanomas, due to the paradoxical activation of the MAPK pathway, specific BRAF inhibitors cannot be used." (PMID 25645078, 2015). "Events activating PI3K in mutated NRAS and BRAF-driven melanomas (i.e. PTEN loss), further expand the requirement of RAB7 and the roles of macropinocytosis (e.g. scavenging nutrients such as albumin and amino acids, lipids and extracellular ATP) to a broader spectrum of melanocytic lesions." (PMID 26008978, 2015). "For instance, Wilmott and colleagues reported different subclones in tumor tissue from a single metastatic site in a BRAF-mutant melanoma patient, following progression of disease after seven months of treatment with the BRAF inhibitor vemurafenib; one clone had an additional NRAS mutation." (PMID 25886620, 2015). "In summary our findings suggest that prenylation inhibition may be able to target melanoma cells with mutant NRAS or with mutant BRAF and PTEN." (PMID 25646931, 2015). "NRAS and BRAF mutations are believed to be mutually exclusive in melanoma." (PMID 26201960, 2015). "Gender distribution, age, site and Breslow thickness of primary melanoma was not statistically associated with BRAF or NRAS mutational status." (PMID 26305188, 2015). "Importantly, when mutant β‐catenin is expressed in BrafV600E/Pten‐/‐‐ or NRas‐driven melanoma in mice, this significantly enhances the development of metastasis." (PMID 25818589, 2015). "Importantly, the majority of melanoma cases demonstrate oncogenic activation of the KIT—NRAS—BRAF—MEK—ERK central axis that is a major regulator of cell differentiation and proliferation." (PMID 25646931, 2015). "Indeed, in a mouse melanoma model, hemizygous PTEN loss synergized with NRAS mutation and led to bypass of senescence." (PMID 26307673, 2015). "Importantly, this link appears to be maintained in melanoma where oncogenic BRAF or NRAS hyperactivates the MAPK pathway." (PMID 25818589, 2015). "More important, the concept of targeted treatment of NRAS mutant melanoma could be demonstrated within clinical trials." (PMID 26544513, 2015). "An additional study has also implied that the presence of NRAS mutations has a negative influence on survival in stage IV melanoma patients." (PMID 24959217, 2014). "Interestingly, IPA3 specific PAK inhibitor is able to inhibit the proliferation of melanoma and CRC cells with mutations at KRAS or NRAS better, than those containing mutations at BRAF." (PMID 25361007, 2014). "Interestingly, the BRAF fusions in melanoma are exclusive of other known oncogenic events such as BRAF and NRAS mutations." (PMID 25204415, 2014).